TRAPPC6A (trafficking protein particle complex subunit 6A)
Description:
May play a role in vesicular transport during the biogenesis of melanosomes.
Synonyms: HSPC289; TRS33; MGC2650
Tractability: PROTAC: ubiquitination databases record sites on it; its protein half-life has been measured.
Gene: Protein-coding gene on chromosome 19 (45,162,928 to 45,178,265, reverse strand). Ensembl gene ENSG00000007255.
Subcellular location: Golgi apparatus, cis-Golgi network; Endoplasmic reticulum
Pathways (Reactome):
Vesicle-mediated transport: COPII-mediated vesicle transport; RAB GEFs exchange GTP for GDP on RABs
Gene Ontology:
Molecular function: protein binding
Biological process: COPII vesicle coating; endoplasmic reticulum to Golgi vesicle-mediated transport; Golgi vesicle transport
Cellular component: cis-Golgi network; cytoplasm; cytosol; trans-Golgi network; TRAPPIII protein complex; endoplasmic reticulum; Golgi apparatus
Genetic constraint (gnomAD): Loss-of-function variants: 25 observed, 17.49 expected, observed/expected ratio (o/e) 1.43, 90% interval 1.03 to 1.88. The upper end of that interval is the gene's LOEUF score, 1.88, which puts it in group 6 of 6, group 1 being the genes least tolerant of losing a copy. Missense variants: 215 observed, 200.32 expected, observed/expected ratio (o/e) 1.07, 90% interval 0.96 to 1.2. Synonymous variants: 96 observed, 89 expected, observed/expected ratio (o/e) 1.08, 90% interval 0.91 to 1.28.
Homologues: Orthologues: chimpanzee TRAPPC6A (100% identical), pig TRAPPC6A (92% identical), dog TRAPPC6A (91% identical), guinea pig TRAPPC6A (85% identical), mouse Trappc6a (83% identical), rat Trappc6a (82% identical), zebrafish trappc6bl (57% identical), tropical clawed frog trappc6a (53% identical), Drosophila melanogaster Trs33 (44% identical), Caenorhabditis elegans trpp-6 (43% identical). Paralogues in human: TRAPPC6B (56% identical).
Diseases named in the same sentence as TRAPPC6A in open-access papers:
TRAPPC6A is named in the same sentence as 4 diseases in open-access papers, as found by Europe PMC text mining. Sharing a sentence is not in itself a finding about the gene and the disease. The quoted sentences say what the papers report.
Alzheimer disease (1 paper, 2020). A progressive, neurodegenerative disease characterized by loss of function and death of nerve cells in several areas of the brain leading to loss of cognitive function such as memory and language. "Remarkably, Zfra restores memory loss and suppresses the symptoms of Alzheimer’s disease (AD) in triple transgenic mice by reducing aggregate formation for TRAPPC6A, TIAF1, tau, and amyloid beta proteins." (PMID 32764489, 2020).
Obesity (1 paper, 2024). Accumulation of substantial excess body fat. "However, patients bearing mutations of Trappc2, Trappc2l, Trappc4, Trappc6A/B, or Trappc10 do not develop obesity as patients with Trappc9 mutations do." (PMID 38889014, 2024).
genetic disorder (1 paper, 2018). "We shed new light on the role of another TRAPP complex protein (TRAPPC6A) potentially involved in a genetic disorder with neurodevelopmental features." (PMID 29391579, 2018).
neurodevelopmental disorder (1 paper, 2018). A behavioral and cognitive disorder with onset during the developmental period that involves impaired or aberrant development of intellectual, motor, or social functions. "In addition, the presence of the same cT319A homozygous mutation in TRAPPC6A in the GME database, which is enriched for genes involved in neurodevelopmental disorders, lends further support to the notion that the mutation in TRAPPC6A is the underlying cause for the phenotype we are reporting." (PMID 29391579, 2018). "The homozygous mutation (c.T319A) in TRAPPC6A in a Saudi family reported in this study, is also present in one individual from the Turkish Peninsula, according to the GME database which is enriched for patients with neurodevelopmental disorders from the Middle East." (PMID 29391579, 2018). "In summary, TRAPPC6A potentially adds to a growing list of TRAPP complex proteins (TRAPPC2, TRAPPC9, TRAPPC11), including the closely related TRAPPC6B, involved in neurodevelopmental disorders." (PMID 29391579, 2018).